GOLPH3L (golgi phosphoprotein 3 like)
Description:
Phosphatidylinositol-4-phosphate-binding protein that may antagonize the action of GOLPH3 which is required for the process of vesicle budding at the Golgi and anterograde transport to the plasma membrane.
Synonyms: GPP34R
Tractability: Antibody: UniProt places it where antibodies can reach, with high confidence. PROTAC: ubiquitination databases record sites on it; its protein half-life has been measured.
Gene: Protein-coding gene on chromosome 1 (150,646,228 to 150,697,219, reverse strand). Ensembl gene ENSG00000143457.
Subcellular location: Golgi apparatus, Golgi stack membrane; Golgi apparatus, trans-Golgi network membrane
Subcellular location (Human Protein Atlas): Golgi apparatus; Cytosol
Gene Ontology:
Molecular function: cargo adaptor activity; phosphatidylinositol-4-phosphate binding; protein binding
Biological process: Golgi organization; positive regulation of protein secretion; protein targeting to Golgi apparatus; Golgi to plasma membrane protein transport; Golgi vesicle budding; retrograde vesicle-mediated transport, Golgi to endoplasmic reticulum
Cellular component: Golgi apparatus; cytosol; Golgi cisterna; Golgi membrane; trans-Golgi network; trans-Golgi network membrane; Golgi cisterna membrane
Genetic constraint (gnomAD): Loss-of-function variants: 12 observed, 12.78 expected, observed/expected ratio (o/e) 0.94, 90% interval 0.6 to 1.51. The upper end of that interval is the gene's LOEUF score, 1.51, which puts it in group 6 of 6, group 1 being the genes least tolerant of losing a copy. Missense variants: 136 observed, 174.67 expected, observed/expected ratio (o/e) 0.78, 90% interval 0.68 to 0.9. Synonymous variants: 60 observed, 68.06 expected, observed/expected ratio (o/e) 0.88, 90% interval 0.71 to 1.09.
Homologues: Orthologues: chimpanzee GOLPH3L (100% identical), macaque GOLPH3L (99% identical), pig GOLPH3L (96% identical), guinea pig GOLPH3L (96% identical), rabbit GOLPH3L (96% identical), dog GOLPH3L (95% identical), mouse Golph3l (95% identical), rat Golph3l (95% identical), tropical clawed frog golph3l (80% identical), Drosophila melanogaster sau (64% identical), zebrafish golph3l (64% identical), Caenorhabditis elegans Y47G6A.18 (57% identical). Paralogues in human: GOLPH3 (68% identical).
Diseases named in the same sentence as GOLPH3L in open-access papers:
GOLPH3L is named in the same sentence as 13 diseases in open-access papers, as found by Europe PMC text mining. Sharing a sentence is not in itself a finding about the gene and the disease. The quoted sentences say what the papers report.
ovarian carcinoma (4 papers, 2019 to 2025). A malignant neoplasm originating from the surface ovarian epithelium. "Mechanistically, GOLPH3L has been reported as an activator of the NF-κB signaling pathway in ovarian cancer." (PMID 33509226, 2021). "Additionally, previously known eRNA‐QTLs were successfully recovered, such as rs72700813, which modulates GOLPH3L eRNA (GOLPH3Le) expression and is related to GOLPH3L, a prognostic biomarker for epithelial ovarian cancer." (PMID 39950845, 2025). "Golgi phosphoprotein 3-like (GOLPH3L) is a prognostic biomarker of cervical cancer and ovarian cancer and may be a mitochondrial biogenesis marker in breast cancer metabolism." (PMID 33509226, 2021). "It had been found that the prognosis of ovarian cancer patients with high expression of GOLPH3L was lower than that of patients with low or no expression of GOLPH3L." (PMID 31921678, 2019). "For the two ovarian cancer samples, dpCNV gets 225 cytobands and 128 cytobands, 285 genes and 529 genes overlapped with the COSMIC database, respectively, in which there are many important tumor driver genes corresponding to ovarian cancer, such as PUM1, GOLPH3L, PIWIL4, and KNDC1." (PMID 33519925, 2020).
breast carcinoma (3 papers, 2021 to 2023). "To understand the mechanism by which GOLPH3L promotes tumorigenesis, we combined metabolomic analysis and transcriptome sequencing in GOLPH3L-silenced T47D breast cancer cells." (PMID 33509226, 2021). "Since GOLPH3L knockdown decreased the proliferation of breast cancer cells, we evaluated the impact of GOLPH3L on metabolism and found that the suppression of GOLPH3L expression decreased glycolytic activity in breast cell lines." (PMID 33509226, 2021). "We assessed the expression and biological function of GOLPH3L in breast cancer by combining bioinformatic prediction, metabolomics analysis and RNA-seq to determine the GOLPH3L-related pathways involved in tumorigenesis." (PMID 33509226, 2021). "Our findings suggest that GOLPH3L functions as an oncogene in breast cancer by promoting cellular proliferation and migration and suppressing apoptosis." (PMID 33509226, 2021). "Consistently, compared to the normal breast epithelial cell line MCF-10A, the expression levels of GOLPH3L mRNA and protein were increased in breast cancer cell lines, especially in T47D and BT474 cells." (PMID 33509226, 2021). "Phosphatidylinositol-4-phosphate-binding protein GOLPH3L is overexpressed in human ductal carcinoma of the breast, and its expression levels correlate with the prognosis of breast cancer patients." (PMID 33509226, 2021). "We found that miRNA-1185-2-3p, the expression of which is decreased in human breast cancers and is inversely correlated with the prognosis of breast cancer patients, is directly involved in suppressing the expression of GOLPH3L." (PMID 33509226, 2021). "We demonstrated that knockdown of GOLPH3L in human breast cancer cells significantly suppressed their proliferation, survival, and migration and suppressed tumor growth in vivo, while overexpression of GOLPH3L promoted aggressive tumorigenic activities." (PMID 33509226, 2021). "Furthermore, the overexpression of SERPINE1 reversed the antitumor activities induced by the suppression of GOLPH3L in breast cancer cell lines." (PMID 33509226, 2021). "To determine the impact of miRNA-1185-2-3p on the expression of GOLPH3L, we used miRNA mimics and inhibitors to demonstrate that the expression levels of miRNA-1185-2-3p were inversely correlated with the expression of GOLPH3L in breast cancer lines." (PMID 33509226, 2021). "Therefore, GOLPH3L promotes glucose metabolism in breast cancer and is conducive to SERPINE1 stabilization." (PMID 33509226, 2021). "Moreover, the expression levels of GOLPH3L were inversely correlated with the prognosis of human breast cancer patients." (PMID 33509226, 2021). "To explore the explicit roles of GOLPH3L in breast tumorigenesis, we investigated the mRNA and protein expression levels of GOLPH3L in breast cancer tissues and paired adjacent normal tissues as well as in various breast cancer cell lines and normal breast epithelial cell lines." (PMID 33509226, 2021). "Correspondingly, high-throughput transcriptome sequencing revealed that GOLPH3L expression could markedly alter the expression of 205 genes in breast cancer cells, and the central carbon metabolism pathway was one of the downregulated pathways in GOLPH3L-knockdown cancer cells." (PMID 33509226, 2021).
breast carcinoma (continued). "Therefore, GOLPH3L-mediated stabilization of SERPINE1 could represent an important oncogenic pathway in the glucose metabolism of breast cancer." (PMID 33509226, 2021). "In addition, the protein levels of SERPINE1 were correlated with the protein levels of GOLPH3L in breast cancer cells, supporting the notion that GOLPH3L may regulate the expression of SERPINE1." (PMID 33509226, 2021). "Using a coimmunoprecipitation (Co-IP) assay, we confirmed the interaction between GOLPH3L and SERPINE1 in breast cancer cells." (PMID 33509226, 2021). "We discovered a functional pathway linking miR-1185-2-3p, GOLPH3L and SERPINE1 that plays a significant role in glucose metabolism in breast cancer and provides new therapeutic targets for breast cancer treatment." (PMID 33509226, 2021). "Our discovery provides a mechanistic link between miR-1185-2-3p, GOLPH3L and SERPINE1; this pathway plays a significant role in glucose metabolism in breast cancer and may serve as a novel therapeutic target for breast cancer." (PMID 33509226, 2021). "Since miRNA-1185-2-3p suppresses the expression of GOLPH3L in breast cancer cells, we induced it in the breast cancer cell lines T47D and BT474 to determine whether miRNA-1185-2-3p could have the same tumor suppressive effects as GOLPH3L knockdown." (PMID 33509226, 2021).
aneurysm (1 paper, 2026). Bulging or ballooning in an area of an artery secondary to arterial wall weakening. "Golph3l upregulation by Klf5 facilitates TNF‐α and TNFSF12 secretion from AngII‐stimulated VSMCs by inducing Golgi compaction, which is essential for AIP and aneurysm development." (PMID 41317401, 2026).
cervical cancer (1 paper, 2021). A primary or metastatic malignant neoplasm involving the cervix. "GOLPH3L is highly expressed in various tumor tissues and promotes the proliferation of rhabdomyosarcoma cells and is involved in the regulation of proliferation, apoptosis and the cell cycle in cervical cancer cells." (PMID 33509226, 2021).
liver cancer (1 paper, 2019). An epithelial or non-epithelial malignant neoplasm that arises from the liver. "We found COLEC10, GPAA1, CD5L, NCSTN, SNX27, GOLPH3L, and HIST2H2AC genes were associated with worst OS (HR < 1) in female liver cancer patients." (PMID 31216110, 2019).
melanoma (1 paper, 2024). A malignant, usually aggressive tumor composed of atypical, neoplastic melanocytes. "Genes in cluster 8 (GSTO2, LRRC34), 9 (CLPTM1L) and 10 (CTSS, SETDB1, ANXA9, GOLPH3L, HORMAD1, PPIL3, CASP9, ALS2CR12) underlie the association between melanoma and cancers." (PMID 38308491, 2024).
rhabdomyosarcoma (1 paper, 2012). A rare aggressive malignant mesenchymal neoplasm arising from skeletal muscle. "In addition, GOLPH3 and GOLPH3L knockdown by small interfering RNA prevented the proliferation of human rhabdomyosarcoma cell lines." (PMID 23056210, 2012). "Human rhabdomyosarcoma cell lines and biopsy specimens exhibited an increased expression of both GOLPH3 and GOLPH3-like (GOLPH3L) mRNA and protein." (PMID 23056210, 2012).
cancer (6 papers, 2018 to 2026). A tumor composed of atypical neoplastic, often pleomorphic cells that invade other tissues. "Transwell assays revealed that silencing GOLPH3L inhibited the migration of T47D cells, and in contrast, overexpressing GOLPH3L in cells obviously facilitated cancer cell migration." (PMID 33509226, 2021). "KEGG pathway analysis showed that GOLPH3L expression could markedly influence central carbon metabolism in cancer, glycolysis/gluconeogenesis and 61 other pathways." (PMID 33509226, 2021). "The relative mRNA and protein expression of GOLPH3L in cancer tissues was much higher than that in adjacent normal tissues." (PMID 33509226, 2021).
GOLPH3L also shares sentences with these, for which no sentence is quoted: tumor (2 papers); breast tumors (1); ductal carcinoma of the breast (1); neurodegenerative disease (1); thoracic aortic aneurysm (1).